MYC (MYC proto-oncogene, bHLH transcription factor)
Diseases named in the same sentence as MYC in open-access papers (continued):
Sharing a sentence is not in itself a finding about the gene and the disease.
cancer (continued). "c-MYC (hereafter referred to as MYC) is a transcription factor that is frequently deregulated in human cancers." (PMID 25339305, 2014). "AFF4 is reported to serve as a central binding platform for elongation factors in many SEC formations and to target MYC and regulate its expression in cancer cells." (PMID 24466310, 2014). "Oncoprotein CIP2A a Cancerous Inhibitor of PP2A forms an “oncogenic nexus” by virtue of its control on PP2A and MYC stabilization in cancer cells." (PMID 25015035, 2014). "Deletion of MYC ablates tumorigenesis in mouse models ofcolorectal cancer demonstrating that MYC function is essential for colorectal tumorigenesis (Sansomet al, 2007)." (PMID 25253726, 2014). "Multiple in vivo MYC-overexpression cancer murine models further support MYC as a therapeutic target." (PMID 25495526, 2014). "MYC contributes to cancer progression through its involvement in several cellular functions including cell cycle progression, proliferation, differentiation, and apoptosis." (PMID 25339305, 2014). "Taken together, overexpression of MYC proteins likely makes cancer cells more dependent on HR-mediated DNA repair to resolve stalled DNA replication and, consequently, more sensitive to the blockade of DNA repair by R9-caPep." (PMID 24728180, 2014). "Gene expression was validated both in patients' PBMC and in vorinostat-treated human carcinoma xenograft models, and transient repression of MYC was consistently observed." (PMID 24587009, 2014). "Glutaminase (GLS) was shown to be up-regulated in MYC induction cancer cells and inhibition of GLS decreased the cancer cell growth." (PMID 23590835, 2013). "Deregulation of MYC oncoprotein expression is a crucial event involved in the occurrence of different types of malignant tumors." (PMID 23482921, 2013). "Extensive biological data support MYC as an oncogene, and 8q24, harboring MYC, is the most common amplified region across multiple cancer types." (PMID 23393560, 2013). "Previous studies have demonstrated the activation of downstream targets of NANOG, OCT4, SOX2 and MYC genes in aggressively growing human cancers." (PMID 24023739, 2013). "We selected the genes G0S2, CDKN1A and MYC as master examples for demonstrating the complex role of 1,25(OH)2D3 in the control of cellular proliferation in this cancer cell model." (PMID 24202443, 2013). "Though most of the LOH regions encompass known cancer genes including MYC, there are some areas that are still left unexplored." (PMID 24204606, 2013). "Co-amplification of PVT1 and MIR1204 with MYC has been reported in several types of cancers, and their oncogenic roles have been also suggested." (PMID 23716474, 2013). "Since MYC is a well characterized oncogene, we wanted to investigate if hypoxia upregulates expression of MYC also in pluripotent cancer cells." (PMID 24236059, 2013). "MYC is a transcriptional factor involved in cell cycle regulation and cell growth arrest that is commonly deregulated in cancers and has been described as a key element of gastric carcinogenesis." (PMID 24053468, 2013). "Investigators have also identified a link between MYC and miRNAs that also play a significant role in cancer." (PMID 23365639, 2013). "Aminotransferases were required for glutamine to sustain mitochondrial metabolism in MYC-dependent cancer cells, consistent with previous findings that these enzymes predominate over glutamate dehydrogenase in glucose-consuming, proliferating cancer cells." (PMID 24280108, 2013). "The association between dependency on MYC and ATAD2 suggests ATAD2 as a therapeutic target in MYC-dependent cancers." (PMID 23393560, 2013).
cancer (continued). "There is a bulk of evidence accumulated indicating that IGF2BP1 sustains MYC expression in tumor cells derived from various cancers in vitro (e.g.: mammary carcinomas; ovarian carcinomas; colorectal carcinomas)." (PMID 23069990, 2013). "Since, however, oncogenic MYC is only one factor sensitising cancer cells to BET inhibition and considering its high expression levels in most tumours it is not likely that this oncogene will have predictive value for patient stratification." (PMID 23918227, 2013). "EZH2 and HDACs were recently identified as critical histone modifiers of deregulated miRNAs in cancer and can be recruited to a miRNA promoter by transcription factors such as MYC." (PMID 24261995, 2013). "Glutamine-induced mitochondrial respiration is necessary for cell proliferation and survival of MYC-dependent cancer cells compared to their differentiated counterparts." (PMID 24280108, 2013). "It showed to potently stabilize MYC G4 structures in different cancer cell lines, resulting in a decrease of MYC gene transcription and protein expression and, consequently, to affect the expression of factors controlled by MYC, including TERT." (PMID 24108400, 2013). "Taken together, the mRNA expression profiles match that of BCR activated cells with a prominent signature of MYC induction, known to promote proliferation and gene expression in leukemic and other cancer cells." (PMID 23560086, 2013). "We have previously demonstrated that downregulation of DCLK1 can upregulate critical miRNAs in both in vitro and in vivo cancer models and results in downregulation of c-MYC, KRAS, NOTCH1 and EMT-related transcription factors." (PMID 24040120, 2013). "One mechanism, by which both normal and cancer cells meet their metabolic demands for cell proliferation, is through activation of c-MYC (herein termed MYC)." (PMID 24280108, 2013). "Overexpression of MYC induces oncogenic transformation, and its deregulation in multiple human malignancies contributes to a large fraction of human cancers." (PMID 23776131, 2013). "Such a mechanistic association between ATAD2 and MYC, and the finding that MYC-dependent cells are sensitive to ATAD2 knockdown, suggest ATAD2 as a therapeutic target in MYC-dependent cancers." (PMID 23393560, 2013). "Previously, it has been reported that regulation of MYC expression by BET inhibitors in solid tumors is somewhat cancer-type dependent." (PMID 24293458, 2013). "As already indicated, tumors appear to be addicted to c-MYC even if the oncogenic signal is upstream of c-MYC rendering c-MYC an excellent target for cancer therapy." (PMID 24130880, 2013). "Previous data indicate that MYC-dependent cancer cells are dependent on glucose and glutamine for proliferation and survival." (PMID 24280108, 2013). "cMYC was recently established to act as a general amplifier of gene expression in the context of development and differentiation, and in cells expressing abnormally high levels of MYC (i.e. in analogy to cMYC amplification in some cancers)." (PMID 23483971, 2013). "The c-MYC proto-oncogene, which is either amplified or overexpressed, is estimated to be involved in 20% of all human cancers and the c-Myc protein affects expression of nearly 15% of genes in genomes as disparate as flies and humans." (PMID 23634284, 2013). "Previously, we and others have demonstrated that MYC or oncogenic Ras-dependent cancer cells have higher levels of ROS compared to their isogenic immortalized cells." (PMID 24280108, 2013). "We analysed here the structure of rearranged chromosomes 17 bearing an hsr harbouring an amplified MYC region in two human cancer cell lines." (PMID 23821669, 2013).
cancer (continued). "Collectively, these results indicate that MYC-dependent cancer cells have an increased dependence on aminotransferases when compared to their isogenic differentiated counterparts." (PMID 24280108, 2013). "Unfortunately, despite intense research efforts to inhibit MYC activity, this protein has thus far remained an elusive cancer therapy target." (PMID 25374893, 2013). "As a consequence, the possibility to inhibit MYC transcription through G4 stabilization has been actively pursued in several human cancer models using specific small molecules." (PMID 24108400, 2013). "These elements seem to be extremely sensitive to perturbations, i.e. inhibition of BRD4 in cancer cells was found to completely ablate its binding to a super-enhancer of MYC, leading to a significant decrease in the amount of MYC expression." (PMID 23766291, 2013). "Inhibition of the BRD4 protein by JQ1, thus, proved to have effective antitumoral properties, suggesting that targeting MYC expression is feasible in selected cancers." (PMID 24231268, 2013). "The regulatory models of miR-29 and other miRNAs suggest that the well-known transcription factor MYC, which is one of the most commonly overexpressed oncogenes in cancer, has some functions in the aspect of epigenetic regulation." (PMID 24261995, 2013). "In particular, citrate is exported from the mitochondria and utilized for fatty acid synthesis in MYC-dependent cancer cells." (PMID 24280108, 2013). "We therefore investigated the CpG methylation pattern of NANOG (also known as NANOG1), OCT4, SOX2, KLF4 and c-MYC in human cancer cell lines by bisulfite sequencing approach." (PMID 24023739, 2013). "In contrast, cancer cells from other tissue origins, with the exception of HeLa, displayed hypermethylation status of c-MYC exon 3 (ranging from 72% to 99%)." (PMID 24023739, 2013). "The 8q24.21 region contains oncogenes including MYC and amplification of this region is observed in several late-stage/aggressive cancers." (PMID 25374893, 2013). "Our findings, that diclofenac inhibits both glucose metabolism and MYC expression, make this well established drug an attractive candidate for inclusion in clinical trials with likely important implications for cancer therapy." (PMID 23874405, 2013). "Normal cells induce MYC upon cell surface receptor-dependent signaling to stimulate aerobic glycolysis and glutaminolysis to promote cell proliferation, while cancer cells have deregulated MYC allowing proliferation to occur in a cell-autonomous manner." (PMID 24280108, 2013). "As one of the most important cancer-related genes, MYC has been proved to participate in several essential functions, such as cell cycle progression and apoptosis." (PMID 22691419, 2012). "It has been shown that MYC promotes cell cycle progression of cancer cells to enhance an uncontrolled cellular proliferation in various malignances." (PMID 22545051, 2012). "MYC is a powerful cancer-promoting gene but, paradoxically, also shows oncosuppressive activity by inducing apoptosis and cell senescence." (PMID 22580498, 2012). "Over-expression of the MYC proto-oncogene is one of the most common oncogenic events in human cancers." (PMID 23145106, 2012). "Abnormal MYC expression is a common denominator in cancer, and its activation is mediated by insertional mutagenesis, chromosomal translocations and gene amplification, but not by mutations in the coding sequence." (PMID 22580498, 2012). "Since its isolation 27 years ago, MYC has commanded interest worldwide, and nearly 20,000 studies on virtually every form of cancer have been published." (PMID 22580498, 2012). "We chose to inhibit MYC, a known oncogene recently identified as a master regulator of expression of "poor-outcome" cancer signatures." (PMID 23113900, 2012).
cancer (continued). "The human cancer combinatory gene regulatory network is found to be a hierarchical scale-free network with MYC, hsa-miR-106b and has-let-7c being the most important regulators." (PMID 22691419, 2012). "In total 25 genes, including the WRN progeria gene, the MYC cancer gene and the longevity MTOR (also known as FRAP1) gene, were selected for replication analyses." (PMID 22247756, 2012). "The let-7 family of miRNAs (let-7a through let-7h) regulates expression of key oncogenes, such as RAS and MYC, and is specifically down-regulated in many cancer types." (PMID 23167930, 2012). "Chromosomal translocations, isochromosomes, double minute chromosomes (DM), and abnormally banded or homogeneously stained regions (HSRs) are also responsible for MYC deregulation in a variety of cancers." (PMID 22580498, 2012). "MYC participates in release of paused RNA pol II, as c-myc can bind positive elongation factor b (P-TEFb) and stimulate transcriptional elongation in cancer cells." (PMID 22348395, 2012). "The crucial role of MYC has been demonstrated in numerous kinds of human tumors and the regulation of cancer-related gene expression." (PMID 22545051, 2012). "For instance, a quick topology analysis of this network highlights the very important cancer-related transcription factor MYC and two remarkable miRNAs hsa-miR-106b and hsa-let-7c." (PMID 22691419, 2012). "These authors found that the gene expression patterns of cancer and stem cells are similar for the MYC module but significantly different for the other two modules." (PMID 22363642, 2012). "For instance, we discriminated three significantly recurrent coherent FFL motifs from our combinatorial regulatory network, most of which involve the ascertained cancer-related transcription factor MYC." (PMID 22691419, 2012). "Constitutive MYC-dependent activation of a large number of genes involved in a broad range of metabolic processes is responsible for the development of a variety of cancers." (PMID 22754359, 2012). "It is disappointing that after many years of intense effort and despite major advances in understanding the regulation and function of the MYC gene, the development of cancer therapeutics that would target MYC itself remains elusive." (PMID 22580498, 2012). "Several strategies using different kinds of antisense oligonucleotides or peptide nucleic acids have been tested in cell systems and also in mouse strains for their effectiveness in inhibiting the MYC-induced proliferation of cancer cell lines." (PMID 22860051, 2012). "In ER-negative breast cancer, the genetic signature of hormone-driven proliferation can be reproduced in cancers that overexpress MYC." (PMID 23145106, 2012). "We believe that our results constitute a proof-of-concept that manipulating c-MYC expression has therapeutic potential for cancer treatment." (PMID 23028984, 2012). "One of the first indications that PcG proteins play a role in cancer was the identification of BMI1 as MYC-collaborating oncogene." (PMID 22102868, 2011). "Our in vitro experiments provide evidence that c-MYC sensitizes MB cells to some anti-cancer treatments." (PMID 21324178, 2011). "MYC is sufficient to reactivate an ES cell-like gene expression program in normal human cells and human cancer cells." (PMID 21364753, 2011). "First, in the RCC group the over expression of c-MYC in cancers was significantly higher than that of normal tissues." (PMID 21982273, 2011). "c-MYC is known to be an important regulator of cancer cell growth in part by regulating ribosomal biogenesis." (PMID 22046300, 2011). "We show that loss of RB has minimal effects on the development of HCC initiated by the overexpression of MYC, suggesting that these two cancer genes share many functions in liver cells undergoing tumorigenic transformation." (PMID 21573126, 2011).
cancer (continued). "The MYC transcription factor is one of the most potent and commonly deregulated oncoproteins in human cancers." (PMID 22132187, 2011). "MYC immunoreactivity was only observed in the intestinal metaplasia and cancer samples, corroborating our previous study with human samples." (PMID 21811552, 2011). "MYC has been widely presumed as the regulated target gene, but definitive evidence functionally linking these cancer regions with MYC has been difficult to obtain." (PMID 21814516, 2011). "Although MYC belongs to a family of related genes, including MYCN and MYCL, MYC is the most frequently activated member in human cancers." (PMID 22039435, 2011). "A role for ribosome biogenesis in cancer progression comes from the recent observation that c-MYC localizes to nucleoli where it functions as a regulator of ribosome biogenesis." (PMID 21556130, 2011). "Comparison between cells with normal and overexpressed MYC will help to enhance our understanding of how to best use and combine conventional drugs in cancer treatment." (PMID 22132187, 2011). "We found that genes that changed as a result of MYC amplification in cancer had a high overlap with our "secondary target genes" (p-value 10−59)." (PMID 21297939, 2011). "These events include CDKN2A deletion and MYC amplification in immortalization, HRAS activation in transformation, PIK3CA activation in the formation of malignant tumors, and RUNX1 deletion associated with poorly-differentiated malignant tumors." (PMID 20169162, 2010). "By contrast, dosage events affecting genes that promote cancer in allele-independent manner, e.g. loss of CDKN2A or gain of MYC, were expected to display random somatic alterations of either allele." (PMID 20885788, 2010). "MYC is regulated in part through mitogenic stimuli and is activated constitutively in cancer cells through gene amplification, chromosomal translocation, point mutation and mitogenic stimulation." (PMID 20163722, 2010). "By contrast, cancer cells with deregulated MYC enforce a transcriptional growth response that is independent of external cues." (PMID 20300622, 2010). "Deregulation of the c-Myc oncoprotein (hereafter Myc) occurs in many human cancers, generally as a consequence of MYC gene amplification or its aberrant transcriptional regulation." (PMID 21060841, 2010). "Our findings support the targeting of Pim1 in human cancer and suggest a potential for using the same inhibitor (such as 10058-F4) to target both MYC and PIM1 in human tumors." (PMID 20515470, 2010).